GRHL2 (grainyhead like transcription factor 2)
Diseases named in the same sentence as GRHL2 in open-access papers (continued):
Sharing a sentence is not in itself a finding about the gene and the disease.
breast carcinoma (continued). "In our in-depth analysis utilizing chromatin accessibility, we determine the intratumor heterogeneity of breast cancer cells with a focus on ER signaling, and we identify distinct cell populations potentially driven by GRHL2 that may contribute to intrinsic resistance to endocrine therapy." (PMID 35676392, 2022). "Interestingly, ZEB1 binds and represses the GRHL2 promoter in breast cancer." (PMID 32005677, 2020). "Furthermore, overexpression of GRHL2 in breast cancer cell lines showed significant increase in migration, invasion potential and also correlated with unfavorable breast cancer patient characteristics – grade III tumors and large tumor size at the time of diagnosis." (PMID 32974388, 2020). "To confirm that higher GRHL2 expression is an unfavorable metastatic factor related to histological grade of the breast tumor, we evaluated a collection of six independent datasets pertaining to primary human breast cancer, containing 947 independent primary breast tumor samples." (PMID 23441166, 2013). "The role of a master regulator of EMT most convincingly has been demonstrated by the ability of GRHL2 to significantly impede transforming growth factor β- or Twist-induced and spontaneous EMT in breast cancer cells." (PMID 40889682, 2025). "In basal‐like breast cancer, inhibition of KDM4C promotes the recruitment of CTSL to chromatin through the transcription factor GRHL2." (PMID 41261048, 2025). "We find that GRHL2 and CD73 are inversely correlated in a panel of human breast cancer cell lines and human breast cancer patients." (PMID 38706844, 2024). "Studies in malignant tumors such as breast cancer and ovarian cancer have shown that the Zeb1/miR-200s axis is involved in the regulation of EMT by GRHL2." (PMID 39402063, 2024). "GRHL2 is reported to suppress aspects of tumor progression through inhibition of EMT 29 and downregulated at the invasive front of breast cancers." (PMID 39430246, 2024). "GRHL2 binds an intronic NT5E sequence and is negatively correlated with NT5E/CD73 in breast cancer cell lines and patients." (PMID 38706844, 2024). "Here, GRHL2 suppressed EMT mediated by the TGF-β signaling pathway and it was downregulated in EMT-dependent mammary tumours (claudin low, metaplastic) and cell lines (basal-B)." (PMID 35269877, 2022). "It has been previously reported that the pioneers TFs FOXA1 and GATA3 mediated ESR1 binding by shaping enhancer accessibility; FOXA1 collaborates with GRHL2 and MLL3 to establish a targetable collateral pathway in endocrine therapy-resistant breast cancer." (PMID 34395436, 2021). "Together, FOXA1 and GRHL2 induce the expression and activity of LYPD3, a Ly6 receptor family member, as well as its ligand AGR2, in mouse models of endocrine resistant breast cancer, as well as patient tumors that progressed on endocrine therapy." (PMID 34680352, 2021). "GRHL2 levels correlated positively with CDH1 (E-cadherin) levels and negatively with ZEB1 in the CCLE dataset and TCGA datasets from breast cancer, ovarian cancer and colorectal cancer." (PMID 32676163, 2020). "There is only a weak, positive correlation between ESR1 and GRHL2 expression in the TCGA and METABRIC breast cancer datasets." (PMID 31084623, 2019). "The transcription factor grainyhead-like-2 (GRHL2) is involved in the wound-healing response and has been demonstrated to protect from EMT in breast cancer cell models." (PMID 27367735, 2016). "Since FOXA1 contributes to the establishment of enhancer elements that are subsequently used by transcription factors such as ER in these breast cancer cells, we integrated the MLL3, FOXA1, and GRHL2 ChIP-seq data with ER binding information." (PMID 27926873, 2016). "Breast cancer cells derived from MMTV-NEU mouse were induced to undergo EMT in vivo after implanted into syngeneic mice, and Grhl2 is dramatically down-regulated in the cells that have undergone EMT (GSE13259)." (PMID 23284647, 2012).
breast carcinoma (continued). "We next addressed whether the inverse correlation between GRHL2 and NT5E identified in the MCF-7 conditional KO models was observed in a larger series of breast cancer cell lines." (PMID 38706844, 2024). "Having established an inverse correlation between GRHL2 and NT5E/CD73, we asked whether the NT5E gene could be subject to direct transcriptional regulation by GRHL2 in breast cancer." (PMID 38706844, 2024). "Remarkably, the increased adenosine levels triggered by GRHL2 depletion in MCF-7 breast cancer cells do not suppress but mildly increase CD8 T cell recruitment, a response mimicked by a stable adenosine analog but prevented by CD73 inhibition." (PMID 38706844, 2024). "Epithelial markers (e.g., GRHL2, CLDN4 and E-cadherin) are lost in basal B breast cancer cells as compared to the luminal and basal A subtype and we examined whether EHF expression followed this pattern." (PMID 36691073, 2023). "While GRHL2 overexpression was sufficient to induce MET in mesenchymal MDA-MB-231 breast cancer cells, it failed to do so in RD sarcoma cells." (PMID 36864480, 2023). "Like FOXA1, GRHL2 may act as a pioneer factor, promoting chromatin accessibility and GRHL2 has been found to co-occupy enhancer elements with FOXA1, GATA3, and ER⍺ to regulate ER⍺ signaling output in hormone receptor positive breast cancer." (PMID 36691073, 2023). "ZEB1 is canonically repressed by GRHL2 in a negative feedback loop in multiple cancer types, including breast cancer, bladder cancer, and ovarian cancer." (PMID 37761927, 2023). "The results of this study indicate that the role of GRHL2 in luminal versus basal breast cancer cells is similar but not identical." (PMID 36768838, 2023). "Finally, in meta-analysis across multiple transcriptomic datasets belonging to breast cancer, ovarian cancer and bladder cancer, we investigated the correlation of ELF3, GRHL2 and KLF4 with epithelial and mesenchymal gene sets." (PMID 36864480, 2023). "Another study, by scATAC-seq of 12 breast cancer patients, found that the transcription factor GRHL2 cooperates with FOXA1 to initiate endocrine resistance and that epigenetic heterogeneity may contribute to endocrine resistance in breast cancer patients." (PMID 37821906, 2023). "Although there have been no other studies characterising Grhl2 or any other Grhl family members during breast development, one can begin to draw some parallels from existing breast cancer studies that detail a role for GRHL2." (PMID 35269877, 2022). "Similarly, GRHL2 significantly inhibits TGF-β-induced, Twist-induced, and spontaneous EMT in breast cancer." (PMID 34868979, 2021). "We aimed to study the impact of EMT-related markers on a breast cancer cohort and specifically analyze the involvement of Snail, Twist, ZEB1, N-cadherin, Vimentin, GRHL2, E-cadherin, and EpCAM and their respective outcome on both immune infiltration of the TME and clinicopathological features." (PMID 34680248, 2021). "Further, the overexpression of KLF4 in MDA-MB-231 breast cancer cells restored E-cadherin levels, induced an epithelial morphology, and suppressed migration and invasion, similar to previous observations in these cells for another MET-TF, GRHL2." (PMID 34680284, 2021). "We showed that epithelial breast cancer cells have no GRHL2 methylation, whereas mesenchymal basal cell lines displayed moderate to high methylation levels for this marker." (PMID 30154364, 2018). "Additionally, recent studies showed that GRHL2 and CDH1 in human breast cancer cells were highly correlated and suppressed EMT by repressing expression of the ZEB1 gene." (PMID 23887935, 2013). "Using a mouse model of 4T1 and MCF-7 cell lines, we have demonstrated EMT-mediated enhanced metastatic spread of GRHL2-overexpressing cells in a mouse model of breast cancer (data not shown)." (PMID 23441166, 2013).
breast carcinoma (continued). "Basal A subtype tumors expressed very low level of Gata3, but high levels of E-cadherin and Grhl2, indicating Gata3 was not the essential transcription factor that controls E-cadherin expression in human breast cancers." (PMID 23284647, 2012). "In agreement with an earlier report exploring a different panel of cell lines, using RNA-seq data of 52 human breast cancer cell lines we found that GRHL2 mRNA was low or absent in most breast cancer cell lines representing the basal B subtype and expressed in all luminal and basal A cell lines." (PMID 36768838, 2023). "Together, this data indicates that CDH1, ZEB1, and ZEB2 genes do not represent direct transcriptional targets of GRHL2 in luminal breast cancer and their regulation may occur through post-transcriptional regulation in this cellular context." (PMID 36691073, 2023). "As a quality control of the ChIP samples, ChIP-qPCR confirmed the interaction of GRHL2 with the promoter region of CLDN4, a known direct target gene of GRHL2 in all three luminal, GRHL2-positive cell lines but not in the GRHL2-negative Hs578T human basal-B breast cancer cell line." (PMID 36691073, 2023). "In breast cancer, GRHL2 has previously been shown to directly interact with FOXA1, which may contribute to the tethering of the histone methyltransferase MLL3 and, consequently, epigenetic marks at GRHL2/FOXA1 binding sites." (PMID 31084623, 2019). "First, GRHL2 - a well-known regulator of morphogenesis that controls the differentiation and migration of epithelial cell layers - can maintain collective cell migration at its endogenous levels, drives MET when overexpressed, and enables EMT when knocked down in breast cancer cells." (PMID 27008704, 2016). "Moreover, intersection of our identified GRHL2 peaks with published ER⍺ binding events in the same series of luminal breast cancer cells cultured under the same conditions further indicates that GRHL2 binds most of the targets found by us in absence of ER⍺, FOXA1, and GATA3." (PMID 36691073, 2023). "The co-regulation analysis revealed a significant negative relation between GRHL2 and NT5E mRNAs in breast cancer patient tumors with a Spearman value of −0.32 (p < 0.001)." (PMID 38706844, 2024). "Together, these results indicated that CLDN4 is a direct GRHL2 target while CDH1, ZEB1, or ZEB2 are unlikely to represent direct GRHL2 target genes in luminal breast cancer cells." (PMID 36691073, 2023). "Collectively, these data indicate that no matter what signaling pathway induces breast cancer cells to undergo EMT, Grhl2 is always down-regulated." (PMID 23284647, 2012). "Indeed, GRHL2 mRNA was highly expressed in Her2 low and Her2+ luminal lines and, with more variation, in TNBC basal A breast cancer cell lines while it was not or lowly expressed in TNBC basal B cell lines (p < 0.0001); NT5E showed an opposite pattern." (PMID 38706844, 2024). "Gene clusters correlating positively (including known GRHL2 targets such as ErbB3, CLDN4/7) or negatively (including TGFB1 and TGFBR2) with GRHL2 in the MCF7 knockout model, display similar correlation with GRHL2 in ER positive as well as ER negative breast cancer patients." (PMID 36691073, 2023). "Moreover, there were higher observed co-expression scores for FOXM1/E2F1, FOXA1/GRHL2, FOXA1/GATA3, suggesting that absence of FOXA1 might contribute to doxorubicin resistance in breast cancer cells through collaboration with the down-regulated GRHL2 and/or GATA3." (PMID 34395436, 2021).
ovarian carcinoma (18 papers, 2016 to 2024). A malignant neoplasm originating from the surface ovarian epithelium. "Gynecological tumor studies have also demonstrated that increased GRHL2 expression is associated with poor prognosis in ovarian cancer." (PMID 36968845, 2023). "It has also been demonstrated that Grainyhead-like 2 (GRHL2) acts as an EMT suppressor in ovarian cancer." (PMID 39201656, 2024). "Consistently, a prior study indicated that miR‐200 family genes were positively regulated by GRHL2 in ovarian cancer by binding to miR‐200’ promoter or indirectly involving in other signalling pathways through transcriptional regulation." (PMID 32324317, 2020). "GRHL2 knockdown in ovarian cancer cell lines harboring the epithelial phenotype results in a specific shift of subcellular E-cadherin localization with unaltered total E-cadherin protein abundance, generating a partial EMT phenotype." (PMID 32974388, 2020). "GRHL2 has been established as a tumor server through the regulation of cell proliferation, migration, and invasion in multiple cancers, including ovarian cancer and gastric cancer." (PMID 31956297, 2020). "We further demonstrate that EMT induced by GRHL2 knockdown would result in genome-wide epigenetic remodeling similar to that observed in ovarian cancer cells with progressive EMT phenotypes." (PMID 31372511, 2019). "In application to ovarian cancer modeling, suppression of GRHL2 was recently shown to inhibit proliferation, invasion, and migration of ovarian cancer cells, emphasizing the importance of incorporating this factor into a low-dimensional EOC EMT/MET model." (PMID 28792442, 2017). "GRHL2 is highly effective to induce MET in ovarian cancer cells with the intermediate phenotype." (PMID 32974388, 2020). "Our data suggest that inhibiting DNA methylation might enhance the function of GRHL2 in activating the expression of certain target genes in ovarian cancer cells with a full EMT state." (PMID 31372511, 2019). "DNase sensitivity, FAIRE, ATAC-seq, or chromatin capture assays coupled with GRHL2 ChIP experiments will be useful to examine the interplay of GRHL2 and chromatin accessibility of epithelial genes in ovarian carcinoma cells with an intermediate or a full EMT phenotype." (PMID 31372511, 2019). "Therefore, in ovarian cancer cells with intermediate phenotypes, GRHL2 overexpression resulted in partial MET from an intermediate mesenchymal towards an intermediate epithelial state, with the co-expression of E-cadherin and vimentin." (PMID 31372511, 2019). "Specifically, overexpression of GRHL2 has been shown to induce epithelial gene expression, inhibit mesenchymal gene expression, restore metabolic reprogramming caused by EMT, and suppress tumor cell migration/invasion, at least in breast and ovarian cancer cell lines." (PMID 32676163, 2020). "These genes are among those that showed reduced expression and CpG methylation gain in ovarian cancer cells with high EMT score (including HEYA8) and also in GRHL2-knockdown cells." (PMID 31372511, 2019). "Overall, MET effects of GRHL2 overexpression, EZH2 inhibition, and HDAC inhibition were limited in ovarian cancer cells with a full EMT state, as these cells may have additional mechanisms that would hinder the expression of epithelial genes." (PMID 31372511, 2019). "Similarly, ChIP-seq experiments showed no binding of GRHL2 to the Zeb1 or Zeb2 promoters in kidney, placenta, ovarian cancer or lung epithelial cells." (PMID 32005677, 2020).
deafness (14 papers, 2010 to 2023). An inherited or acquired condition characterized by the complete loss of the ability to hear from one or both ears. "Among them were four genes associated with deafness [grainyhead like transcription factor 2 (GRHL2), BCL2 like 11 (BCL2L11), ELMO domain containing 3 (ELMOD3), usherin (USH2A)]." (PMID 32835229, 2020). "SR-285 carried three candidate variants of known deafness genes (p.Q445R in GRHL2, p.T1321S in TECTA, and p.S2161F in MYO15A); only one mutation, p.S2161F in MYO15A, was shared with an affected sibling." (PMID 23865914, 2013). "The granular head-like 2 gene (GRHL2) is located on chromosome 8, and the protein it encodes is a transcription factor that is associated with Deafness, Autosomal Dominant 28 (DFNA28), which is associated with ARHL in Europeans, but not in Han Chinese, which may be due to population differences." (PMID 37730634, 2023). "Among a number of nonsyndromic deafness genes, variants in SLC26A4, COCH, MYO7A, GRHL2, and CLIC5 as well as POU4F3 are known to cause vestibular symptoms and/or dysfunction." (PMID 28545070, 2017). "But the results showed a non-significant enrichment (empirical P > 0.05) for the P-value thresholds from P < 5.0 × 10–02 to P < 5.0 × 10–04.rs2275994, located at 18 kb downstream of GRHL2, was the most significant SNP within the deafness loci (HR = 3.85, 95% CI 2.24–6.61, P = 1.10 × 10–06)." (PMID 37062025, 2023). "In contrast, mutagenesis studies in Grhl2 have indicated a probable different pathophysiology for deafness with enlarged otocysts, absent otoliths, and malformed semicircular canals." (PMID 25152456, 2014). "The significance of GRHL2 in vertebrate inner-ear development is well established, but the lack of deafness in the heterozygotes (and some homozygotes) in our pedigrees indicates a different functional effect of the missense mutations." (PMID 25152456, 2014). "Considering that a second disease-causing mutation has not been reported, one might begin to suspect that GRHL2 is not a bonafide deafness gene." (PMID 23813623, 2013).